HK2 (hexokinase 2)
Diseases named in the same sentence as HK2 in open-access papers (continued):
Sharing a sentence is not in itself a finding about the gene and the disease.
osteosarcoma (continued). "Therefore, further investigation is necessary to elucidate the precise molecular mechanism by which HK2 controls glycolysis in osteosarcoma." (PMID 39661501, 2024). "However, the effects of USP22 knockdown were partially counteracted by HK2 overexpression, suggesting that USP22 promotes glycolysis and cell proliferation in osteosarcoma by upregulating the expression of HK2." (PMID 39661501, 2024). "Recently, a study found that ANGPTL2 could enhance angiogenesis in osteosarcoma by upregulating the expression of hexokinase 2 (HK2) and VEGF." (PMID 39252946, 2024). "Collectively, these results suggest that HK2 mediates glycolysis in osteosarcoma cells via USP22." (PMID 39661501, 2024). "In addition, USP22 knockout reduced the protein expression of β‐catenin and hexokinase 2 (HK2) in osteosarcoma cells." (PMID 39661501, 2024). "Moreover, PI3K-AKT was also reported to induce the Warburg effect via up-regulating HK2 expression and tumorigenic growth in osteosarcoma." (PMID 35216429, 2022). "For example, lncRNA PVT1 could act as a molecular sponge of miR-497, promote the expression of HK2, enhance the uptake of glucose and production of lactate, and promote osteosarcoma cell proliferation." (PMID 36072431, 2022). "Knockdown of lncRNA-TUG1 via targeting HK2 could inhibit glucose consumption and lactate production in osteosarcoma cells." (PMID 33123468, 2020). "It has been reported that lncRNA Pvt1, which is usually regarded as an oncogene, influences the expression of HK2, promoting glycolysis, and tumor progression in osteosarcoma and gallbladder cancer through acting as a competitive endogenous RNA to directly bind to miR-497 or miR-143, respectively." (PMID 31850189, 2019). "Therefore, targeting the USP22/β‐catenin/HK2 axis may be an effective strategy for osteosarcoma treatment." (PMID 39661501, 2024). "Therefore, we speculated that the effect of USP22 on glycolysis in osteosarcoma cells might be related to HK2." (PMID 39661501, 2024). "Therefore, targeting glycolytic enzymes PFKFB3 and HK2 might be a promising therapy for osteosarcoma." (PMID 39252946, 2024). "Additionally, we examined HK2 protein and mRNA expression in 30 osteosarcoma tissue samples." (PMID 39661501, 2024). "Additionally, HK2 mediates USP22‐induced regulation of glycolysis in osteosarcoma cells." (PMID 39661501, 2024). "In addition, RBM15 interacts with circ-CTNNB1 to enhance the expression of HK2, GPI and PGK1 in an m6A modification-dependent manner, leading to the promotion of the glycolytic process and the development of osteosarcoma." (PMID 37474926, 2023). "Therefore, to investigate the molecular mechanism by which USP22 activates HK2 in osteosarcoma cells, we verified whether endogenous USP22 and HK2 directly bind to 143B cells." (PMID 39661501, 2024). "HK2 was a direct target of miR-497, long non-coding RNA PVT1 acts as molecular sponge to repress miR-497, as a result, PVT1 promotes glycolysis and cell proliferation in osteosarcoma and form a PVT1/miR-497 axis in the Warburg effect through regulation of HK2 expression." (PMID 28738810, 2017). "Indeed, we observed that HIF-1 target genes ANGPTL4, VEGFA, GLUT1, PGK1 and HK2 were down-regulated at mRNA level when DEC2 is knocked down in several osteosarcoma cell lines, while the mRNA level of HIF-1α showed no obvious change by the DEC2 knockdown." (PMID 25884381, 2015).
diabetes (29 papers, 2013 to 2026). "There is evidence, therefore, that HK2-linked glycolytic overload occurs at the sites of vascular complications and early-stage embryo in diabetes and this likely contributes to hyperglycemia-linked pathogenesis developing therein in diabetes." (PMID 35216280, 2022). "It was previously shown that HK2 expression is insulin-responsive, and in diabetes mellitus, HK2-associated unscheduled glycolysis may be a key initiator of insulin resistance and the development of vascular complications." (PMID 39044840, 2024). "Thus, we propose that loss of adipose HK2 is a mechanism for selective insulin resistance in liver and ultimately diabetes." (PMID 36920797, 2023). "Increased glycogen deposition at the sites of vascular complications of diabetes is explained by the HK2-linked glycolytic overload and unscheduled glycolysis hypothesis." (PMID 38292764, 2023). "Whilst the HK2-linked glycolytic overload hypothesis appears to offer an improved explanation and prospective new route for therapy of hyperglycemia-induced embryo malformations in diabetes, other factors may be involved." (PMID 40867918, 2025). "HK2-linked glycolytic overload and unscheduled glycolysis offers an improved hypothesis to explain metabolic dysfunction contributing to the development of insulin resistance and the vascular complications of diabetes." (PMID 35216280, 2022). "A condition for the induction of glycolytic overload in hyperglycemia is that HK2 is a major contributor to HK activity at the sites of development vascular complications of diabetes." (PMID 38292764, 2023). "In vascular complications of diabetes, the pharmacological intervention required is to normalize HK2 protein levels to those of euglycemic control." (PMID 38292764, 2023). "It is interesting to speculate that, through the improvement of dysglycemia, metformin may decrease HK2-linked unscheduled glycolysis and thereby contribute to partial improvement in insulin resistance and the prevention of the vascular complications of diabetes." (PMID 35216280, 2022). "Recent research reports suggested that abnormal HK2 increased activity plays a key role when control of glycolysis is impaired, as in the case of diabetes." (PMID 35328751, 2022). "In our study, the mRNA expression of Hk2 was decreased in STZ-induced diabetic retina mice, which was also decreased in the muscle of patients with T2DM." (PMID 36557283, 2022). "In this review, we describe this and evidence that the hypothesis of HK2-linked glycolytic overload and unscheduled glycolysis are likely key initiators of metabolic dysfunction, contributing to the development of vascular complications of diabetes, diabetic embryopathy, and insulin resistance." (PMID 35216280, 2022). "Both peripheral and CNS neurons suffer cytosolic hyperglycemia in diabetes, with GLUT1 and GLUT3 glucose uptake, but only Schwann cells have significant expressions of HK2 and are susceptible to HK2-linked glycolytic overload." (PMID 35216280, 2022). "The combination of metformin, which is approved for the treatment of diabetes, together with HK2 inhibition is an attractive approach for HCC therapy." (PMID 29386513, 2018). "In addition, Nsd2 is downregulated in diabetes mellitus type 2 and has been shown to play a role in insulin secretion and glucose metabolism by regulating hexokinase 2 (HK2) and glucose-6-phosphate dehydrogenase (G6PD)." (PMID 38818037, 2024). "In addition, the diabetes-induced decreases in HK2, PKM2, and LDHA protein levels in mice testis were confirmed by western blot analysis." (PMID 35929593, 2022). "It has been reported that the expression of Hk2 was reduced in skeletal muscle of diabetes." (PMID 31338039, 2019). "Importantly, the expression of HK2 is significantly reduced in diabetes patients." (PMID 36481721, 2022).
diabetes (continued). "The reduced expression of solute carrier family 2, facilitated glucose transporter member 4 (GLUT4) and hexokinase-2 (HK2) in skeletal muscle participates in insulin resistance of diabetes mellitus (DM)." (PMID 30258406, 2018). "After evaluating gene, protein and miRNA expression, using correlation analysis, the results show that miR-29b-3p, miR-29c-3p, miR-199a-5p, and miR-532-3p might be candidates to repress GLUT4 and HK2 expression, which could contribute to glycemic homeostasis impairment in diabetes." (PMID 30258406, 2018). "Correction of the increase in embryonic HK2 protein in high-glucose-concentration cultures by 5–20 μM tRES + HESP suggests that Glo1 inducer treatment may prevent glycolytic overload in the embryo of a mother with diabetes and thus produce a therapeutic response in diabetic embryopathy." (PMID 40867918, 2025). "Furthermore, excessive levels of glycolytic markers, including PFKFB3, HK2, and other key glycolytic proteins, as well as overproduction of lactate, have been reported in vascular endothelial cells inflicted by atherosclerosis, diabetes mellitus, and other vascular lesion-related diseases." (PMID 36425580, 2022). "We identified 8 hub genes (JUN, ATF3, VEGFA, SLC2A1, HK2, PTGS2, PFKFB3, and KLF6) that were enriched in response to hypoxia, angiogenesis, vasculogenesis, hypoxia-induced signaling, cancer, diabetes, and transplant-related disease pathways." (PMID 36482897, 2022). "Diabetes reduced Slc2a4/GLUT4 and Hk2/HK2 expression (50–77%), upregulated miR-29b-3p and miR-29c-3p (50–100%), and downregulated miR-93-5p, miR-150-5p, miR-199a-5p, miR-345-3p, and miR-532-3p (~30%) expression." (PMID 30258406, 2018). "In sum, we report that diabetes altered miR-29b-3p, miR-29c-3p, miR-199a-5p and miR-532-3p expression in muscle of male rats, where their predicted targets Slc2a4/GLUT4 and Hk2/HK2 are repressed." (PMID 30258406, 2018). "HK2 is regulated by AKT signaling, with phosphorylated AKT promoting its mitochondrial translocation to inhibit apoptosis; its transcription is suppressed by high glucose via PPARγ, reducing its protective role in diabetes." (PMID 40940763, 2025). "However, overexpression of circ‐IGF1R increased HK2 and VEGFA expression, and HEV treatment ulcerated tissue in mice with diabetes." (PMID 38984951, 2024). "In diabetes, the Glucokinase gene expression was decreased, whereas Hexokinase 2, Gapdh, and Pkm2 (not significant) were increased; these alterations were reversed by dapagliflozin." (PMID 36809274, 2023). "In diabetes, the miR-532-3p expression might be related to chronic inflammation and oxidative stress, and it might regulate GLUT/HK2 pathway to participate in insulin resistance." (PMID 35291991, 2022). "Hexokinase 2 (HK2; FC = −3.4), succinate dehydrogenase complex, subunit C (SDHC; FC = −3.1), isocitrate dehydrogenase 1 (IDH1; FC = −1.8), and pyruvate kinase muscle (PKM; FC = 1.5) were all downregulated in individuals with diabetes." (PMID 34690929, 2021). "The recent discovery of the glucose-induced stabilization of hexokinase-2 (HK2) to proteolysis in cell dysfunction in model hyperglycemia has revealed a likely key initiating factor contributing to the development of insulin resistance and vascular complications in diabetes." (PMID 35216280, 2022).
lung adenocarcinoma (25 papers, 2013 to 2025). A carcinoma that arises from the lung and is characterized by the presence of malignant glandular epithelial cells. "We found that in patients with lung adenocarcinoma, expression of HK2 and GBE1 were positively associated with tumor size (P=0.0175, P=0.0018), tumor stage (P=0.00174, P=0.003) and TNM classification N staging (P=0.0256, P=0.0249), respectively." (PMID 28423489, 2017). "However, the mechanisms underlying the transcription regulation of HK2 in lung adenocarcinoma need to be further elucidated." (PMID 39119928, 2024). "NSD3 formed protein trimer with PPP1CB and p‐STAT3, thus stimulating p‐STAT3 dephosphorylation by PPP1CB to suppress the transcription of HK2, which ultimately inhibited the Warburg effect in lung adenocarcinoma." (PMID 39119928, 2024). "Meanwhile, NSD3 suppressed glycolysis by inhibiting HK2 translation, transcription, glucose uptake, and lactate production in lung adenocarcinoma." (PMID 39119928, 2024). "In TCGA lung adenocarcinoma database (n = 740), upregulation of some glycolytic enzymes including HK2 gene was reported in FGFR-amplificated cancers, comparing with diploid cancers." (PMID 36168616, 2022). "We found that GBE1 and HK2 expression pattern has a highly positive correlation with HIF1α in lung adenocarcinoma and squamous carcinoma patients." (PMID 28423489, 2017). "In terms of prognostic features, a survival analysis revealed that the high GBE1 and HK2 expression group exhibited poorer survival in lung adenocarcinoma patients." (PMID 28423489, 2017). "This includes activating the expression of genes known to induce malignancy (ATAD2 (ATPase family AAA domain containing 2)) and genes that have been implicated in reduced survival in lung adenocarcinoma patients (GBE1 (glycogen branching enzyme), HK2 (hexokinase 2))." (PMID 36831404, 2023). "Recently, the overexpression of ATAD2 was found to be positively correlated with the expression of maximum standardized uptake value (SUVmax), total lesion glycolysis (TLG), glucose transporter protein 1 (GLUT1), and hexokinase 2 (HK2) in lung adenocarcinoma (LUAD) tissues." (PMID 36008934, 2022). "Integrated analyses of RNA-seq and ChIP-seq to access BACH1 targets using lung adenocarcinoma identified that BACH1 activates transcription of hexokinase 2 (HK2) and Glyceraldehyde 3-phosphate dehydrogenase (GAPDH) at their promoters as a transcriptional activator." (PMID 33809182, 2021). "Furthermore, we used publicly available datasets to validate that the late-stage lung adenocarcinoma patients showed higher expression HK2 and GBE1 than early-stage ones." (PMID 28423489, 2017). "Furthermore, a significant association emerged between expressions of GBE1/HK2 and the lung adenocarcinoma, but not lung squamous carcinoma in our analysis." (PMID 28423489, 2017). "Finally, we examined whether glucose transporter-1 (GLUT1) and hexokinase 2 (HK2) expression was associated with 18F-FDG uptake, and assessed the correlation between PKM2 and GLUT1 and HK2 in lung adenocarcinomas." (PMID 28489603, 2017). "Moreover, the protein expression levels of Fasn, Shmt1, Arg1, and Hk2, that have important functions in cell proliferation and growth, were studied by Western blot analysis and these experiments confirmed their up-regulation in lung adenocarcinomas." (PMID 27602772, 2016). "Cells expressing high levels of HK2 were identified in both cytokeratin (CK)-positive and CK-negative CTC populations isolated from lung adenocarcinoma patients." (PMID 36768924, 2023). "In lung adenocarcinoma, EGFR mutant tumor tended to show lower HK2 expression than EGFR wild type tumor (P = 0.079)." (PMID 36320008, 2022). "BUB1B knockdown could decrease the glycolysis-related genes, including solute carrier family 2 number 1, LDHA, pyruvate kinase M 2, and hexokinase 2, suggesting that BUB1B acts as an activator in glycolytic metabolism to promote lung adenocarcinoma." (PMID 38711083, 2024).
lung adenocarcinoma (continued). "The survival analysis revealed that in lung adenocarcinoma patients, the ones with high expression of GBE1 and HK2 represented shorter overall survival than those with low expression of GBE1 (P=0.0332) and HK2 (P=0.0246), evidence supporting an association between these genes and cancer survival." (PMID 28423489, 2017). "The protein expression of glycolysis‐related enzymes (HK2, LDHA and GLUT1) was confirmed to be decreased in PFD‐treated lung adenocarcinoma cells (A549 and H1299) but not in PFD‐treated lung squamous carcinoma cells by western blotting." (PMID 38140828, 2024).
lymphoma (24 papers, 2013 to 2025). A malignant (clonal) proliferation of B- lymphocytes or T- lymphocytes which involves the lymph nodes, bone marrow and/or extranodal sites. "Importantly, using tissue samples from lymphoma patients, we show that HK2 expression is strongly associated with development of B cell lymphoma." (PMID 29335581, 2018). "GLUT1 and hexokinase 2 were overexpressed in lymphoma cells and the microenvironment, while FAP was stromal." (PMID 40417720, 2025). "A recent study identified Proviral Insertion in Murine Lymphomas 2 (PIM2) directly binding to hexokinase-II (HK-2) and phosphorylating HK2 on Thr473." (PMID 36776368, 2022). "For example, in EBV-associated lymphoma cells, the EBV membrane oncoprotein LMP1 regulates glucose metabolism by upregulating the enzymes involved in glucose metabolism, such as HK2, PDK, and PKM2, through the activation of HIF1 alpha." (PMID 32727118, 2020). "The co-cultivated lymphoma cells showed increased anaerobic glycolysis, indicated by increased expression of hexokinase 2 (HK2) and pyruvate dehydrogenase kinase (PDK)." (PMID 31454887, 2019). "HK2 expression was highly induced in lymphoma cell lines compared with a normal B cell line GM02184 and primary B-cells derived from normal lymphoid tissue." (PMID 29335581, 2018). "Screening of human primary DLBCL patient samples determined that HK2 is significantly correlated with lymphoma phenotype." (PMID 29335581, 2018). "Western blot analysis showed that HK2 protein expression was induced at all time points in lymphoma cell lines exposed to hypoxia compared to those grown under normoxia." (PMID 29335581, 2018). "Controversially, the other studies have suggested higher expression of HK2 in lymphoma tissues; therefore, these discrepancies could be the result of different sample sizes in alternative studies." (PMID 35265223, 2022). "Interestingly, NK-cells displayed upregulated Ki-67, HK2, and CPT1α levels during engraftment that remained elevated in the patient group with r/r lymphoma." (PMID 35794135, 2022). "Among these, many inhibit enzymes that have been identified as potential therapeutic targets in lymphomas such as hexokinase 2 (HK2), which catalyzes the first committed step in glycolysis, or mitochondrial dihydroorotate dehydrogenase, which is important for pyrimidine synthesis." (PMID 36428647, 2022). "Confusingly, there are different data suggesting that HK2 may be highly expressed in both lymphoma and normal tissue samples, and it is speculated that this may be due to different sample sizes." (PMID 34708035, 2021). "To further conclusively check if HK2 alters tumorigenic potential and its relevance to hypoxic environment, we studied the effect of HK2 knockdown on lymphoma growth in vitro in presence of hypoxia and in vivo using animal xenograft model, which mimics tumor microenvironment." (PMID 29335581, 2018). "This suggests that HK2 expression correlates with hypoxic tolerance of lymphoma cells." (PMID 29335581, 2018). "Our data clearly determine the clinical relevance of HK2 in lymphoma progression." (PMID 29335581, 2018). "Targeting HK2 resulted in decreased mitochondrial membrane potential, ATP production, cell viability, and re-sensitization to chemotherapy agents, suggesting that overexpression of HK2 could be a novel potential therapeutic target in rituximab-refractory lymphomas." (PMID 33409153, 2020). "HK2 expression may influence prognosis in lymphoma patients." (PMID 29335581, 2018). "Furthermore, we have demonstrated that HK2 contributes to lymphoma development." (PMID 29335581, 2018). "Immunohistochemistry staining results showed that hexokinase 2 (HK2) and glucose transporter 1 (GLUT1) cell densities were significantly higher than FAP in most lymphoma subtypes (p < 0.001)." (PMID 39595051, 2024). "WTAP induces the expression of its critical target gene, hexokinase 2 (HK2), by enhancing HK2 m6A level, thereby promoting lymphoma progression." (PMID 37568728, 2023).